CD86 (CD86 molecule)
Diseases named in the same sentence as CD86 in open-access papers (continued):
Sharing a sentence is not in itself a finding about the gene and the disease.
tumor (continued). "Immunologic adjuvants can stimulate DC maturation, enhancing the expression of MHC-II, CD40, and CD86, thereby improving the generation of tumor-specific CD8+ T cells and promoting tumor suppression." (PMID 40813760, 2025). "FeAMV treatment elicited superior DC maturation (CD11c+CD86+ cells) versus monotherapies, achieving maximal tumor growth inhibition and M1/M2 polarization, confirming combinatorial ferroptosis–bacterial immunotherapy efficacy." (PMID 40892295, 2025). "We demonstrate using ex vivo 3D tumor models and novel in vivo cell tracking models that radiation results in upregulation of the costimulatory molecules CD80 and CD86 on tumor macrophages and on monocytes that enter the tumor following radiation." (PMID 41417245, 2025). "To investigate the intra-T and peri-T topography and the link of macrophages (CD68+) and tumor B cells (CD20+) with CD86 and CSF1-R expression, we performed IF staining of DLBCL and non-tumor control samples in the same TMAs." (PMID 41415285, 2025). "Immune profiling showed CWP + X-ray + aPD-L1 treatment enhanced mature DCs (CD80+CD86+) by 24.5% and tumor-infiltrating CD8+ T cells by 4.8% versus controls, confirming enhanced antitumor immunity through ICD potentiation." (PMID 40892295, 2025). "Regarding their phenotypes, CD86+ cDC1 were more frequently detected than CD86+ cDC2 in tumor tissue, with 44.44 ± 10.62% and 7.72 ± 4.84%, respectively." (PMID 41221283, 2025). "Since CD86 can activate not only effector T cells but also Treg cells, it is possible that in CLL, the tumor cells suppress the T‐cell immune response via the CD86‐Treg connection, and the anti‐tumor response capability of the immune system is reduced." (PMID 40635602, 2025). "In the present study, an expression of CD86 in tumor cells was accompanied by an increased number of Casp-3 expressing cells in HS in lung and skin." (PMID 40271486, 2025). "Looking at the DC phenotypes in more detail, pDC and cDC1 in tumor tissues and to a lesser extent in liquid samples demonstrated a more mature phenotype based on significantly higher proportions positive for CD86 and CD40." (PMID 41221283, 2025). "Similar to the results observed in the balb/c nude model, an elevation of CD86 expression was observed in tumor tissues of mice treated with NCTD." (PMID 40394236, 2025). "Immunofluorescence assays corroborated these findings, revealing a reduced percentage of CD86+ M1 macrophages and an increased percentage of CD163+ M2 macrophages and CD4+Foxp3+ Treg cells in mutated tumor tissues." (PMID 40384867, 2025). "Consistent with the in vitro results, both ITZ and ICI monotherapy significantly reduced tumor weight and volume in mice tumor model and increased the proportion of CD86+ M1-type TAMs while reducing CD206+ M2-type TAMs." (PMID 40697374, 2025). "Inhibitory molecules expressed by tumor cells (such as PD-L1 and CD86) bind to checkpoint receptors on immune cells, thereby restricting anti-tumor immune responses." (PMID 40072049, 2025). "To address alternative sources of CD80 and CD86 in the tumor environment, we profiled expression of these markers along with PDL1 (CD274) in published scRNASeq data from five different murine tumors including MC38." (PMID 41417245, 2025). "In contrast we found a significantly longer BMS with high CD86 expression in the tumor nest of the cerebral metastases in our cohort." (PMID 40510346, 2025). "The impact of lactate on TME tumor evasion has also been observed with HLA-DR- and CD86-high macrophages have a glycolytic phenotype that suppresses the secretion of anti-tumor IL-12 p70 via PKM2/HIF-1α axis." (PMID 40092297, 2025). "Consistently, we also observed significant increase in the CD86+ DCs population after the treatment of SAN-TLRa together with BMAA in the tumor tissue." (PMID 40083927, 2025).
tumor (continued). "IHC analysis of 53 GC pathological samples revealed that the number of tumor-infiltrating CD86+ M1 macrophages was significantly lower in GC tissues than in paracancerous tissues and that the number of CD206+ macrophages was significantly greater." (PMID 40858547, 2025). "They suggest that tumor-infiltrating M1 (CD86+) and M2 (CSF1-R+) macrophages have a peri-T location and that more macrophages (CD68+) than DLBCL cells (CD20+) express these two markers." (PMID 41415285, 2025). "In contrast, we found no disparities in the expression of the markers CD68, CD163, and CD86 within the tumor nest across the entire cohort." (PMID 40510346, 2025). "Studies show that CD80 acts as a functional ligand for CTLA-4, particularly in tumour models where CD80-transfected tumours exhibit reduced immunogenicity compared to those with CD86." (PMID 40725864, 2025). "We found that treatment with NOC47‐Ce6+Laser significantly upregulated various M1‐associated markers in the tumor tissues, including CD80, CD86, and IL family cytokines." (PMID 40287972, 2025). "Unsupervised clustering of spectral flow cytometry data of the CD11b+ CD45+ population revealed an increase in Clusters 1 and 3 in IFNγRKO tumours, which represent a population of monocytes characterised by Ly6Chi CD86+ or CD62L+." (PMID 39746898, 2025). "Using these models, we demonstrate that radiation results in significant upregulation of the costimulatory molecules CD80 and CD86 on monocytes and macrophages in the tumor, and on monocytes that are recruited to the tumor following radiation." (PMID 41417245, 2025). "Our results showed that NCTD increased CD86 levels within tumor tissues of NCTD-treated mice and promoted macrophage polarization to the M1 phenotype in vitro." (PMID 40394236, 2025). "The mRNA expression of tumor-supportive macrophage genes, such as Arg-1, was reduced by shTRIM32-CM, whereas the expression of cytotoxic response genes IL-1β, IL-12 A, and CD86 was elevated by shTRIM32 cell supernatants." (PMID 41163195, 2025). "Pomalidomide also reverses EBV- and KSHV-mediated immune evasion by restoring the expression of MHC I, ICAM-1, and CD86 on tumor cells." (PMID 40647389, 2025). "The results of the present study are consistent with the mechanisms described in the literature and suggest an anti-tumor effect of CD86 mediated by immune cells." (PMID 40271486, 2025). "Then, the analysis of CYPJ, CD86 and CD8 positive cells in 61 paired LIHC tumors and adjacent normal tissues showed that the positive cells of CYPJ and CD86 were significantly up-regulated in tumor tissue compared with adjacent normal tissues." (PMID 40520002, 2025). "Grouping all vaccinated mice together, the percentage of CD86+ and CD206+ tumor-associated macrophages (TAMs) was significantly lower in the vaccinated groups compared to that of the PBS control group (p = 0.0124 and p = 0.046, respectively)." (PMID 41322193, 2025). "In the same model, the MI formulations also increased the expression of CD86 and HLA-DR, two markers of M1 anti-tumor macrophages." (PMID 40362536, 2025). "Bcl-2 expression was significantly lower in the CD68+ macrophage compartment compared with the CD20+ tumor cell compartment, but was correlated with M1 (CD86+) macrophage infiltration." (PMID 41415285, 2025). "The fraction of CD8+ T cells was lower, while the infiltration rate of immunosuppressive CD56+CD16− NK cells and CD163+CD86+ M2-like macrophages were significantly enriched in all 4 tumor entities." (PMID 40274631, 2025). "The overall survival rate of the group with high numbers of tumor-infiltrating CD86+ M1 macrophages was significantly higher." (PMID 40858547, 2025). "In the present study, we reconfirmed this idea by showing a significant increase in the proportion of CD86+ DC cells in tumor tissues after VVL-TD-mIL-27 treatment at day 6, and this phenomenon was also observed in lymph nodes and spleens." (PMID 40350204, 2025).
tumor (continued). "The Akt inhibitor alone significantly reduced tumor growth in our model, increased the proportion of CD86+ M1 macrophages, decreased M2 macrophages, and elevated CD86 expression on DCs." (PMID 41378083, 2025). "The resulting IFN‐γ‐TEX vaccine significantly increased F4/80+CD86+ M1 macrophages in tumor tissues reflecting immunological effects driven by IFN‐γ signaling." (PMID 41256221, 2025). "In particular, the data indicate a stronger immunosuppressive role of CD80 compared to CD86 in a tumor tissue context, suggesting the exploration of anti-CTLA-4 and anti-CD80 antibody combinations in animal models." (PMID 40725864, 2025). "Upon binding to CD80 (B7-1) or CD86 (B7-2) on antigen-presenting cells or tumor cells, it functions as an inhibitory switch." (PMID 40677703, 2025). "These macrophages are characterized by markers such as CD86, and human leukocytes antigen (HLA)-DR, and are involved in the destruction of tumor cells and the inhibition of tumor growth." (PMID 40362536, 2025). "Recently an effect of CD80 and CD86 on tumor regression in canine cutaneous histiocytoma has been described." (PMID 40271486, 2025). "In a recent study, a comparable CRISPRa technique was utilized to simultaneously activate multiple endogenous genes such as Cd70, Cd80, Cd86, Ifnα4, Ifnβ1, and Ifnγ, triggering anti-tumor adaptive immune clearance of tumor cells in a mouse model." (PMID 41283440, 2025). "Treatment with 177Lu-DOTA-TATE in human bronchial neuroendocrine tumors enhances the infiltration of CD86+ APCs into the tumor microenvironment." (PMID 40725216, 2025). "After the mice were sacrificed, T cells and macrophages were analyzed using flow cytometry; dual co-blockade increased significantly the percentage of M1 macrophages in the tumor microenvironment, followed by an increase in expression of CD86+ and TNFα+." (PMID 41096863, 2025). "Preclinical models show that LILRB2 blockade reprograms myeloid cells to a pro-inflammatory phenotype, enhances MHC-II and CD86 expression, and synergizes with anti–PD-1 therapy to improve T cell infiltration and tumor regression." (PMID 40821795, 2025). "Further fluorescent staining of CD31, CD206, and CD86 confirmed the polarization of macrophages and provided additional evidence of reduced vascular density and altered macrophage populations within the tumor microenvironment." (PMID 40665352, 2025). "Our results show a higher expression of CD68 in the tumor stroma of brain metastases, whereas CD86 and CD163 showed comparable levels in both locations." (PMID 40510346, 2025). "This was associated with a reduction in Treg proportions in the tumor, and the authors similarly conclude that costimulation by CD80 and CD86 is more important for Treg than for the other T cells involved in tumor control." (PMID 41417245, 2025). "Inosine significantly increased M1 macrophage markers CD86 and iNOS and enhanced the anti-tumor activity of M1 macrophages, effectively inhibiting CRC progression and metastasis potential." (PMID 39795180, 2024). "We identify an upregulation of CD80 and/or CD86 in tumor tissue of (r/r) diffuse large B cell lymphoma (DLBCL) patients treated with tisagenlecleucel." (PMID 38340727, 2024). "Recent reports have suggested that the CD28/CD86 axis in a tumor context is necessary to prevent final CD8 T cell exhaustion and its accumulation.." (PMID 38812523, 2024). "We found that CD44+TCF-1–CD8+ T cells in the tumor after combined RT and CD86 blockade expressed PD-1, albeit to a lesser extent than did CD44+TCF-1+CD8+ T cells." (PMID 38349740, 2024). "Tumor regression caused by cps therapy is associated with high‐level expression of T‐cell receptor costimulatory molecules CD80 and CD86 and IL‐12 and IFN‐γ, which are crucial for activating antitumor T‐cell immunity." (PMID 38109851, 2024). "M1 phenotype TAMs (M1-TAMs), as seen by CD86 staining, were more distributed in tumor tissues in the JHU-083 treatment group compared with the control group." (PMID 38386265, 2024).
tumor (continued). "Macrophage colony-stimulating factor (M-CSF), TGF-β, and vascular endothelial growth factor (VEGF) from primary tumor supernatants of breast cancer-induced healthy donor blood monocytes to differentiate into CD163-high CD86-low IL-10-high M2-like macrophages." (PMID 39199574, 2024). "We analyzed the CD86 expression level of CD11c+ MHC class II+ cells in tumor-draining lymph nodes to determine the activation of APCs." (PMID 39033176, 2024). "CTLA4 is upregulated in activated regulatory T cells (Tregs) and can bind to CD80 or CD86 on the surface of antigen-presenting cells, thus “shutting down” tumor immunity." (PMID 39091494, 2024). "The IHC staining suggested that the expression levels of SLC16A1 and CD206 were found to be significantly elevated in HCC tissues compared to non-tumor tissues, whereas the expression level of CD86 was relatively diminished in HCC tissues." (PMID 39247822, 2024). "Consistent with the in vitro results, the proportion of mature DCs (CD11C+CD40+, CD80+, or CD86+) in tumor tissues and tumor-draining lymph nodes (TDLNs) was highly upregulated compared to that in the control group." (PMID 38994018, 2024). "Consistent with recent findings, most tumor-infiltrating B cells were in cluster 1, which exhibited a highly activated phenotype, expressing Cd86 and Cxcr4." (PMID 39718828, 2024). "Inhibition of the Treg response facilitated tumor-reactive CTL priming and tumor control by RT upon CD86 blockade." (PMID 38349740, 2024). "We also confirmed prominent CD11c and CD86 activation at Mg cell membrane, mainly in the tumor core of three PDOXs confirming antigen presentation cell (APC)-like features." (PMID 38566128, 2024). "(F–I) The protein expression of CD4, CD8, CD86, and Granzyme in tumor tissues is detected by Western blot." (PMID 38441416, 2024). "The CD86 stromal LI showed significantly higher levels in both the invasive front (p < 0.001) and the tumor core (p < 0.001) in BCC as compared to cSCC." (PMID 39329753, 2024). "Overall expression of CD80 in CCH was similar to that in HS (73.3 ± 37.4% vs 62.1 ± 46.4%), while significantly more CD86 expressing tumor cells were found in CCH (94.7 ± 10.3%) when compared to HS (57.6 ± 11.0%)." (PMID 39619201, 2024). "In contrast, CD86 was expressed by 94.7% of CCH tumor cells, but only in 57.6% of HS tumor cells (p = 0.0004) (mean value across all stages)." (PMID 39619201, 2024). "Some reports suggest that CD86 is predominantly expressed on M2 macrophages because M0 and M2 macrophages are the major components of tumor-infiltrating immune cells in OS tissue." (PMID 39199574, 2024). "Individual positive regulatory co-stimulatory molecules (CD70, CD83, CD86) were mainly upregulated in the irradiated tumor of hRT/lena-treated mice." (PMID 38646638, 2024). "Alongside this, administration of A. vulgaris extract significantly increased the percentages of CD40+ and MHCII+ as well as MHCII+CD86+ dendritic cells in the spleens of tumor-bearing mice." (PMID 38543072, 2024). "CTLA4, a T-cell co-stimulatory molecule, primarily functions by binding with co-stimulatory molecules CD80/CD86, thereby inhibiting T-cell activity and weakening immune response, ultimately promoting tumor growth and metastasis." (PMID 38227081, 2024). "M1 TAMs promote immune-mediated anti-tumor activity via the production of CD86 and inducible nitric oxide synthase (iNOS), which contributes to the Th1 response in the tumor microenvironment." (PMID 38611749, 2024). "Compared to splenic myeloid cells, we observed remarkable co-expression of I-A/I-E, CD80, and CD86 with Dectin-1 in tumoral myeloid cells in both tumour models." (PMID 38668817, 2024). "In contrast to larger variations in CD80 expression, mean percentages of CD86 expressing tumor cells among biological replicates were remarkably close to each other in HS between 51.7% and 62.7%." (PMID 39619201, 2024).
tumor (continued). "Our results revealed that 40% and 100% irradiated tumor cells increased the proportion of CD80+ CD86+ DCs compared to the control." (PMID 39736508, 2024). "This was evidenced by increased levels of tumor‐infiltrating neutrophils, the polarization of M2 macrophages toward proinflammatory M1 macrophages, overexpression of CD86 in tumor‐draining lymph nodes, and increased numbers of CD8+ T cells." (PMID 38525112, 2024). "The fluorescence expression of the M2 marker CD163 increased with the elevation of tumor stage, whereas the expression of the M1 marker CD86 was elevated in tumor tissues with lower tumor stages." (PMID 39531417, 2024). "Studies have highlighted that HBO has a marked effect on macrophage phenotype, shifting the balance from the tumor-promoting M2 state toward the tumoricidal M1 state, as indicated by increased expression of CD86 and decreased expression of CD206." (PMID 39061957, 2024). "There is little evidence in the literature to support the use of CD80 and CD86 immunohistochemistry in tumor immunity and prognosis." (PMID 37614091, 2024). "The increase in CD86 expression indicates a shift towards the M1 macrophage phenotype, which is known for its tumoricidal activity and ability to stimulate anti-tumor immune responses." (PMID 39061957, 2024). "M1 (CD86+ CD163-) is a pro-inflammatory phenotype with anti-tumor activity, while M2 (CD86-CD163+) is an immunosuppressive cell type and is thought to have TAMs (tumor-associated macrophage) phenotype in solid tumors that can promote tumor progression." (PMID 38206974, 2024). "RT plus PD-1 blockade increases the Treg response, which is overruled by CD86 blockade, resulting in improved tumor control." (PMID 38349740, 2024). "In an OSCC xenograft mouse model, the knockdown of IL37 resulted in a slower tumour growth rate, accompanied by an increase in the number of CD86+ M1 macrophages and a decrease in CD206+ M2 macrophages." (PMID 39500733, 2024). "PD-1/L-1, CTLA-4, and CD80/CD86 interactions are two crucial immune checkpoint pathways in the tumor microenvironment (TME)." (PMID 38791528, 2024). "The bindings of PD-1 and CTLA-4, expressed on activated T cells, to their ligands on tumor cells (PD-L1) or antigen-presenting cells (APCs) (CD80/CD86) restrain the anti-tumor T cell activities." (PMID 38280003, 2024). "The findings revealed a higher prevalence of CD206+ macrophages in tumour tissues when compared to CD86+ macrophages." (PMID 39500733, 2024). "Mature DCs highly express MHC I and MHC II, CD80, CD86, and pro-inflammatory factors, activating the anti-tumor immunity." (PMID 39364399, 2024). "In concert with the improved tumoural immunity, Let-7i treatment also significantly increased CD86 expression in antigen presenting cells (APCs) in the draining lymph nodes, indicating enhanced APC activity." (PMID 38554167, 2024). "The immunotherapeutic antibodies directed against these immune checkpoint molecules, such as nivolumab, ipilimumab, and pembrolizumab, reactivate the cytotoxic T cells to eradicate tumor cells via blocking the PD-L1/PD-1 or CTLA-4-CD80/CD86 signaling pathways." (PMID 38280003, 2024). "The DC/tumor fusion cells that we produced had strong expression of maturity-associated markers (MHC II, CD80, and CD86) as well as both types of fluorescence." (PMID 38824143, 2024). "Our findings suggested that inosine significantly increased M1 macrophage markers CD86 and iNOS in the tumor microenvironment and enhanced the anti-tumor activity of M1 macrophages, effectively inhibiting CRC progression and metastasis potential." (PMID 39795180, 2024). "The treatment of HCC mouse tumor tissues with B. thetaiotaomicron and acetic acid resulted in upregulated expression of CD86 and NOS2, along with downregulated expression of CD163 and ARG1, as demonstrated by real-time PCR data and flow cytometry data." (PMID 38270111, 2024).